Y_RNA (Y RNA )
Gene: Miscellaneous RNA gene on chromosome 5 (41,963,868 to 41,963,969, reverse strand). Ensembl gene ENSG00000199487.
Homologues: Orthologues: chimpanzee Y_RNA (96% identical), macaque Y_RNA (93% identical). Paralogues in human: RNY3 (86% identical), Y_RNA (86% identical), RNY3P1 (85% identical), RNY3P14 (85% identical), Y_RNA (85% identical), Y_RNA (84% identical), RNY3P11 (83% identical), Y_RNA (83% identical), RNY3P7 (82% identical), Y_RNA (82% identical), RNY3P9 (81% identical), Y_RNA (81% identical), and 91 more.